LINC03122 (long independently transcribed non-coding RNA 3122)
Synonyms: C5orf64; FLJ37543; LINC03119
Gene: Long non-coding RNA gene on chromosome 5 (61,595,713 to 61,808,593, forward strand). Ensembl gene ENSG00000178722.
Subcellular location: Secreted
Diseases named in the same sentence as LINC03122 in open-access papers:
LINC03122 is named in the same sentence as 8 diseases in open-access papers, as found by Europe PMC text mining. Sharing a sentence is not in itself a finding about the gene and the disease.
LINC03122 shares sentences with these, for which no sentence is quoted: tumor (4 papers); lung adenocarcinoma (2); cancer (1); colorectal cancer (1); glioma (1); lung carcinoma (1); psoriasis (1); pulmonary tuberculosis (1).